GALNT4 (polypeptide N-acetylgalactosaminyltransferase 4)
Description:
Catalyzes the initial reaction in O-linked oligosaccharide biosynthesis, the transfer of an N-acetyl-D-galactosamine residue to a serine or threonine residue on the protein receptor. Has a highest activity toward Muc7, EA2 and Muc2, with a lowest activity than GALNT2. Glycosylates 'Thr-57' of SELPLG.
Synonyms: GalNAc-T4; GALNACT4
Tractability: Small molecule: a structure with a bound ligand is known. Antibody: UniProt predicts a signal peptide or a membrane-spanning region. PROTAC: ubiquitination databases record sites on it.
Gene: Protein-coding gene on chromosome 12 (89,519,412 to 89,524,796, reverse strand). Ensembl gene ENSG00000257594.
Subcellular location: Golgi apparatus membrane
Subcellular location (Human Protein Atlas): Golgi apparatus
Pathways (Reactome):
Metabolism of proteins: O-linked glycosylation of mucins
Gene Ontology:
Molecular function: manganese ion binding; polypeptide N-acetylgalactosaminyltransferase activity; protein binding
Biological process: protein O-linked glycosylation via N-acetyl-galactosamine; protein O-linked glycosylation
Cellular component: extracellular exosome; Golgi apparatus; perinuclear region of cytoplasm; Golgi membrane
Genetic constraint (gnomAD): Loss-of-function variants: 19 observed, 42.87 expected, observed/expected ratio (o/e) 0.44, 90% interval 0.31 to 0.65. The upper end of that interval is the gene's LOEUF score, 0.65, which puts it in group 2 of 6, group 1 being the genes least tolerant of losing a copy. Missense variants: 731 observed, 704.86 expected, observed/expected ratio (o/e) 1.04, 90% interval 0.98 to 1.1. Synonymous variants: 257 observed, 258.08 expected, observed/expected ratio (o/e) 1, 90% interval 0.9 to 1.1.
Homologues: Orthologues: pig GALNT4 (93% identical), mouse Galnt4 (91% identical), tropical clawed frog galnt4 (76% identical), zebrafish poc1bl (71% identical), Caenorhabditis elegans gly-5 (42% identical), Drosophila melanogaster Pgant5 (39% identical), Drosophila melanogaster Pgant9 (38% identical), Caenorhabditis elegans gly-3 (37% identical). Paralogues in human: GALNT12 (55% identical), GALNT6 (44% identical), GALNT3 (44% identical), GALNT13 (40% identical), GALNT1 (40% identical), GALNT15 (38% identical), GALNT10 (38% identical), GALNT2 (37% identical), GALNT5 (37% identical), GALNT14 (36% identical), GALNT11 (36% identical), GALNT16 (36% identical), and 7 more.
Diseases named in the same sentence as GALNT4 in open-access papers:
GALNT4 is named in the same sentence as 18 diseases in open-access papers, as found by Europe PMC text mining. Sharing a sentence is not in itself a finding about the gene and the disease. The quoted sentences say what the papers report.
breast carcinoma (4 papers, 2016 to 2023). "In breast cancer, GALNT4, GALNT6, and GALNT8, have been reported to be associated with patient outcomes, whereas no other study examines the clinical role of GALNT1." (PMID 37444599, 2023). "A high probability of recurrence-free survival (RFS) was correlated with a high GALNT4 expression level, indicating the function of this gene in breast cancer progression." (PMID 33234595, 2021). "How does the vesicle trafficking genes SYTL5, RAB27B, SNX24 and SLC12A2 cooperate with GALNT4 to mediate the 17β-estradiol (E2) signaling in breast cancer cells is another key question." (PMID 27322213, 2016). "GALNT4 was one of GALNTs, which showed differential expression level in breast cancer." (PMID 33234595, 2021). "To investigate whether ppGalNAc-T4 is functionally involved in regulating the aggressiveness of breast cancer cells, we used online data sets (GEPIA and Kaplan–Meier) to validate GALNT4 (gene name of ppGalNAc-T4) expression." (PMID 33234595, 2021).
hepatocellular carcinoma (4 papers, 2021 to 2023). A malignant tumor that arises from hepatocytes. "Further investigations showed that GALNT4 attenuates the stemness and anchorage-independent survival of hepatocellular carcinoma cells in vitro and inhibits cancer cell growth in vivo partly via inactivating epidermal growth factor receptor (EGFR)." (PMID 33435156, 2021). "In hepatocellular carcinoma, miR-9-5p levels are elevated, and this miRNA enhances the stemness and anoikis resistance of cancer cells by targeting polypeptide N-acetylgalactosaminyltransferase 4 (GALNT4)." (PMID 33435156, 2021). "miR-9 could directly interact with GALNT4 to repress its expression, while Hnf4α elevated GALNT10 levels through the downregulation of miR-122 in hepatitis B virus (HBV)-infected hepatoma cells." (PMID 37193819, 2023).
prostate carcinoma (2 papers, 2021 to 2023). A carcinoma that arises from epithelial cells of the prostate gland. "For instance, miR-506-3p restrains GALNT4 expression to impede prostate cancer cell proliferation and metastasis." (PMID 36470227, 2023).
acute monocytic leukemia (1 paper, 2016). Acute monoblastic leukemia (AML-M5), is one of the most common subtypes of acute myeloid leukemia (AML) that is either comprised of more than 80% of monoblasts (AML-M5a) or 30-80% monoblasts with (pro)monocytic differentiation (AML-M5b). "In myeloid cells, the expression of GALNT2, GALNT4, GALNT5 and GALNT7 was observed in K562 cells (chronic myeloid leukemia line), and of GALNT1, GALNT2, GALNT3 and GALNT4 in SHI-1 (acute monocytic leukemia line)." (PMID 27322213, 2016).
breast tumor (1 paper, 2021). "The results showed that in Lum subtype, GALNT4 was significantly upregulated in breast tumors compared with that in the normal breast tissues." (PMID 33234595, 2021).
cardiac hypertrophy (1 paper, 2021). "The goal of this work was to elucidate the function of polypeptide N-acetylgalactosaminyltransferase 4 (GALNT4) in myocardial hypertrophy and its underlying mechanism of action." (PMID 34675184, 2021). "Two cardiac hypertrophy models were established through partial transection of the aorta in GALNT4-knockout (GALNT4-KO) mice and adeno-associated virus 9-GALNT4 (AAV9-GALNT4) mice." (PMID 34675184, 2021). "Therefore, our work aimed to investigate the function of GALNT4 in cardiac hypertrophy and its underlying mechanism of action." (PMID 34675184, 2021). "However, whether GALNT4 is a regulatory factor in pathological cardiac hypertrophy, and its possible underlying mechanism remains unknown." (PMID 34675184, 2021). "Taken together the data strongly suggest that GALNT4 regulates cardiac hypertrophy via the MAPK axis." (PMID 34675184, 2021). "Based on these data, we concluded that GALNT4 modulates cardiac hypertrophy and cardiac fibrosis through the ASK1-JNK/p38 signaling pathway." (PMID 34675184, 2021). "Our study indicated that GALNT4 is upregulated during the pathological process of cardiac hypertrophy." (PMID 34675184, 2021). "In conclusion, we have explored the role of GALNT4 on the inhibition of cardiac hypertrophy through the ASK1 signaling pathway." (PMID 34675184, 2021). "To explore the role of GALNT4, we first measured its levels in cell and animal models of cardiac hypertrophy." (PMID 34675184, 2021). "The results suggested that GALNT4 was highly expressed in mouse and cardiomyocyte models of pathological cardiac hypertrophy." (PMID 34675184, 2021). "Furthermore, markers of myocardial hypertrophy and fibrosis were higher in GALNT4-KO mice than those in WT mice." (PMID 34675184, 2021). "Here, we summarize the function of GALNT4 and its regulation of pathological cardiac hypertrophy." (PMID 34675184, 2021). "Furthermore, we found that ASK1 is the downstream core target of GALNT4 that regulates cardiac hypertrophy." (PMID 34675184, 2021). "Overexpression of GALNT4 mitigates cardiac hypertrophy and cardiac fibrosis, suggesting that GALNT4 may be a promising target for the treatment of cardiac hypertrophy." (PMID 34675184, 2021). "We next investigated the signaling pathway by which GALNT4 regulates cardiac hypertrophy." (PMID 34675184, 2021). "GALNT4 directly interacts with ASK1 to reduce the phosphorylation of the ASK1 pathway, thereby regulating cardiac hypertrophy." (PMID 34675184, 2021). "The GALNT4-KO mice demonstrated accelerated cardiac hypertrophy, dysfunction, and fibrosis, whereas the opposite phenotype was observed in AAV9-GALNT4 mice." (PMID 34675184, 2021). "Collectively, GALNT4 inhibits the JNK/p38 cascade by negatively regulating the activation of ASK1, thereby regulating cardiac hypertrophy." (PMID 34675184, 2021). "Our work demonstrates that GALNT4 is a negative regulatory factor of myocardial hypertrophy and that it does not play a role under physiological conditions." (PMID 34675184, 2021). "We also found that GALNT4 could bind to ASK1 and inhibit its oligomerization and phosphorylation to regulate cardiac hypertrophy." (PMID 34675184, 2021). "Furthermore, we demonstrated that GALNT4 could directly bind to ASK1, inhibiting the dimerization and phosphorylation of ASK1 and mitigating cardiac hypertrophy by inhibiting the ASK1 axis." (PMID 34675184, 2021).
clear-cell renal cell carcinoma (1 paper, 2016). "Immunohistochemical detection of GalNAcT4 in renal tumor cells of relapse-free surviving patients with clear-cell renal cell carcinoma (ccRCC) strongly suggested that GALNT4 expression is a positive prognostic factor." (PMID 27322213, 2016).
liver cancer (1 paper, 2021). An epithelial or non-epithelial malignant neoplasm that arises from the liver. "In addition, in liver cancer, GALNT4 has been shown to modulate the activation of EGFR, and a decrease in the miR-9/GALNT4 axis has also been shown to promote the malignant transformation of liver cells." (PMID 34675184, 2021).
Myocardial fibrosis (1 paper, 2021). "Following H&E and PSR staining, GALNT4-KO mice showed a larger cardiomyocyte area and more obvious myocardial fibrosis." (PMID 34675184, 2021).
cancer (5 papers, 2021 to 2023). A tumor composed of atypical neoplastic, often pleomorphic cells that invade other tissues. "Downregulation of GALNT4 resulted in enhanced cancer cell migration and invasion via EMT, while GALNT4 overexpression showed the opposite effect." (PMID 34069424, 2021).
tumor (2 papers, 2022). "By contrast, in hepatocellular carcinoma, GALNT4 behaves as a tumor-restraining enzyme, inhibited by miR-9." (PMID 36555445, 2022). "In prostate cancer and NSCLC, GALNT4 behaves as a tumor-promoting gene." (PMID 36555445, 2022).
infection (1 paper, 2021). The state of being infected such as from the introduction of a foreign agent such as serum, vaccine, antigenic substance or organism. "GALNT4 expression was suppressed following infection of cardiomyocytes with an adenoviral short hairpin RNA targeting GALNT4 (AdshGALNT4)." (PMID 34675184, 2021). "GALNT4 levels were increased following infection with adenoviral GALNT4 (AdGALNT4)." (PMID 34675184, 2021).
GALNT4 also shares sentences with these, for which no sentence is quoted: cervical cancer (1 paper); chronic myeloid leukemia (1); colon cancer (1); endometriosis (1); non-small cell lung carcinoma (1); ovarian carcinoma (1).